EP300 (EP300 lysine acetyltransferase)
Diseases named in the same sentence as EP300 in open-access papers (continued):
Sharing a sentence is not in itself a finding about the gene and the disease.
leukemia (83 papers, 2004 to 2026). A malignant (clonal) hematologic disorder, involving hematopoietic stem cells and characterized by the presence of primitive or atypical myeloid or lymphoid cells in the bone marrow and the blood. "Deletion or translocation of Ep300 gene and point mutations in Ep300 gene are associated with a variety of cancers, including leukemia and solid tumors." (PMID 32765954, 2020). "EP300 encodes a histone acetyltransferase, whose altered transcriptional and epigenetic functions were associated to leukemia and other cancers." (PMID 26046463, 2015). "Thus, rhTPO might suppress the association between EP300 and CREB by competitive binding EP300 in leukemia cells." (PMID 35768562, 2022). "EP300/CREBBP inhibitor selectively exerted potent anti-leukemia activity through blocking the MLL-r-BET complex binding to H3K27Ac modification on critical genes loci, distinct from global histone acetylation." (PMID 38693103, 2024). "Targeting EP300/CREBBP holds great promise for treating leukemia with some certain cytogenetic abnormalities." (PMID 38693103, 2024). "We then analyzed the selective dependency on EP300 and CREBBP of a series of leukemia compared to other tumor cells in DepMap database, highlighting EP300/CREBBP potential targeting in AML cells." (PMID 38693103, 2024). "SEs are enriched in CREBBP/EP300 compared to conventional enhancers, and EP300 recruits BRD4 in mouse leukemia cells." (PMID 34298959, 2021). "We report that the bromodomains of the histone acetyltransferases CREBBP/EP300 are critical to sustain the proliferation of human leukemia and lymphoma cell lines." (PMID 29884215, 2018). "Here, we explore the antiproliferative properties of CREBBP/EP300 bromodomain inhibition in leukemia and lymphoma cell lines and explore the molecular mechanisms responsible for such effects, using both chemical and genetic approaches." (PMID 29884215, 2018). "Rare human leukemias have been found with oncogenic fusion proteins containing either CBP or EP300, and these oncogenic fusion proteins require the activity of CBP or EP300." (PMID 26731516, 2016). "Notably, the TF ERG has been reported to recruit EP300, a transcriptional co‐activator, to influence leukemia transmission." (PMID 40959205, 2025). "We found that the proliferation and colony formation functions of MLL-r AML cells were suppressed significantly upon loss of EP300 or CREBBP, while, the proliferation of the MLL wild-type cells was less influenced, highlighting a specific vulnerability of MLL-r leukemia to EP300/CREBBP depletion." (PMID 38693103, 2024). "Moreover, SE activity of TCF3-HLF is mediated through the recruitment of EP300; thus, BRD4 inhibitor JQ1 and EP300 inhibitor A-485 are two reasonable options for TCF3-HLF-fusion leukemia." (PMID 39090713, 2024). "Importantly, this effect was specific to MLL-r cells, exhibiting minimal impact on MLL wild-type AML cell and normal hematopoiesis, and highlighting the potential of EP300/CREBBP as selective therapeutic targets for this aggressive leukemia subtype of MLL-r." (PMID 38693103, 2024). "Genetic abnormalities of CREBBP/EP300 are also common in leukemia." (PMID 36831561, 2023). "The presence of distinct epigenetic landscape in LSCs from MLL (KMT2A)‐rearranged (MLLr) leukaemias, for example, aberrant H3K4me2/3 patterns and/or EP300 associated pervasive enhancer malfunction, separate LSC from non‐self‐renewing progeny of leukaemia cells." (PMID 37872885, 2023). "Thus, rhTPO suppressed GPX4 expression through blocking the interaction between EP300 and GPX4 gene promoter via associating with EP300 in leukemia cells." (PMID 35768562, 2022). "In addition, other histone acetyltransferase classes, including CBP and EP300, were previously reported to be involved in chromosomal rearrangements in leukemia patients, driving disease formation." (PMID 33594072, 2021).
leukemia (continued). "Importantly, CREBBP and EP300 are also found as oncogenic fusion partners of the histone acetyltransferase gene MOZ or MLL in leukemia." (PMID 31552175, 2019). "Similarly, inhibition of CREBBP/EP300 BRDs specifically affected differentiation of leukemia-initiating cells after prolonged exposure." (PMID 27757418, 2016). "Notably, the TF ERG has been reported to recruit EP300, affecting leukemia transmission." (PMID 40959205, 2025). "However, the precise role of EP300/CREBBP in MLL-r leukemia remains largely unexplored." (PMID 38693103, 2024). "In addition, p300 can play an antitumour role in epidermal tumours, osteosarcoma, myelodysplastic syndrome (MDS)-associated leukaemia and human papilloma virus (HPV)-positive head and neck squamous cell carcinoma (HNSCC), and tumours with high EP300 mutation rates have enhanced antitumour immunity." (PMID 36979352, 2023). "In addition, EP300- and CREBBP-ZNF384 fusions resulted in loss of histone lysine acetyltransferase activity with concomitant global reduction of histone acetylation and increased sensitivity of leukemia cells to histone deacetylase inhibitors." (PMID 33816270, 2021). "Our research underscored the synergistic effect of EP300 and CREBBP in regulating MLL-r leukemia cell proliferation." (PMID 38693103, 2024). "HMGN1 overexpression increases chromatin accessibility, expression, and H3K27ac at loci important for HSCs and leukemia, including many CREBBP/EP300 targets." (PMID 36831561, 2023). "Some pluripotency genes were also identified, as well as cancer genes, such as TET1, ALK, EP300, ERG, MKL1 and PHF6, already described as being involved in leukemia." (PMID 37174060, 2023). "In validation of these findings, known CREBBP/EP300 dependent cancer types (i.e., PCa, lymphoma, myeloma, and leukemia) all ranked highly for CREBBP/EP300 dependency versus other cancer types." (PMID 34199844, 2021). "The role for EP300 in cancer is implied by the fact that it is targeted by oncoproteins, it is fused to MLL in leukemia, and two missense sequence alterations in EP300 have been identified in epithelial malignancy." (PMID 28725161, 2017). "Thus, while CBP/EP300 bromodomain inhibition may have robust cytotoxic effects in multiple myeloma, our results do not exclude the possibility that this modality would have additional therapeutic utility in leukemia by targeting leukemic self-renewal." (PMID 26731516, 2016). "Moreover, we provided a proof of concept that targeting EP300/CREBBP is a potential therapeutic for MLL-r AML, as validated by in vitro and in vivo leukemia models." (PMID 38693103, 2024). "Importantly, targeting the bromodomain of EP300/CREBBP has shown promising efficacy in several malignancies driven by transcriptional activator-driven malignancies, including leukemia, lymphoma and myeloma." (PMID 38693103, 2024). "Collectively, our study identified EP300/CREBBP as a critical epigenetic driver of MLL-r leukemia and validated their therapeutic potential through targeting inhibition, offering a promising avenue for improving clinical outcomes in this aggressive leukemia." (PMID 38693103, 2024). "Simultaneous targeting of EP300/CREBBP and BET had synergistic anti-leukemia effects in MLL-r AML." (PMID 38693103, 2024). "Among other common events in this type of cancer are mutations in genes that encode enzymes modifying histones, such as the histone acetyltransferases CREBBP (CREB Binding Protein) and EP300 (E1A Binding Protein P300), as well as the histone methyltransferases MLL (Mixed Lineage Leukemia)." (PMID 38203275, 2023).
colorectal cancer (59 papers, 2006 to 2026). A primary or metastatic malignant neoplasm that affects the colon or rectum. "Frequent microsatellite instability and consequent loss of EP300 expression has been reported in gastric and colorectal cancers." (PMID 26325386, 2015). "Several lines of evidence showed that EP300 had mononucleotide repeats in exons 27 and 31, which might be mutation targets in gastric and colorectal cancers with microsatellite instability." (PMID 35242279, 2022). "Several studies revealed that aspirin induces autophagy in murine hepatocarcinoma, sarcoma, and colorectal cancer cells, and inhibits histone acetyltransferase (EP300) to induce autophagy." (PMID 33329515, 2020). "The EP300 gene has been previously observed in gastric, breast, pancreatic, and colorectal cancers." (PMID 35723313, 2022). "On the other hand, EP300 overexpression has been described to be associated with poorer outcome and higher aggressiveness in several tumors including HNSCC and cutaneous squamous cell carcinomas, colorectal cancers and hepatocellular carcinoma." (PMID 32523042, 2020). "Thus, the inability of colorectal cancer cells to divert glucose away from metabolism into glycogen storage underpins the cell-type–specific activation of the glucose/ROS/AMPK/EP300/β-catenin axis." (PMID 32603375, 2020). "However, the frequency and role of somatic mutations of EP300 in colorectal cancer is not fully elucidated, but an association with microsatellite instability (MSI) is described in the literature." (PMID 39307893, 2024).
lung carcinoma (59 papers, 2012 to 2025). "An altered methylation pattern was detected in the promoters of ABCB1, ABCC1, and ABCG2 in breast and lung cancer, whereas the defective activity of histone acetylases including EP300, CBP, and PCAF was reported to be implicated in ABCB1 overexpression." (PMID 35205642, 2022). "We utilized both HNSCC and lung-cancer cell lines (which also harbor mutations in either CREBBP or EP300)." (PMID 34732714, 2021). "Interestingly, the blocking of EP300’s phosphorylation was reported to decrease the proliferation and metastasis activity of lung cancer cells." (PMID 28390392, 2017). "Interestingly, inactivation of chromatin modifier p300, a homolog of the histone acetyltransferase CREBBP, has been associated with deregulation of MYC transcription in lung cancer cell lines, and loss of MYC expression in the context of CREBBP and EP300 loss is synthetically lethal." (PMID 31097695, 2019). "They identified EP300 as a key mediator of SOX2 expression, and CBP30, which is an EP300 inhibitor, reduced MGH7 and ChaGoK1 lung cancer cell growth in vitro." (PMID 38612911, 2024). "The other genes AR, ATF2, CUL1, EP300, GATA4, LEF1, SKP2 in these subnetworks have also been identified as important in lung cancer." (PMID 24369052, 2013). "Similar to HNSCC lines, treatment with A-485 generally led to more profound radiosensitization in CREBBP/EP300 mutant but not wild-type lung-cancer cell lines." (PMID 34732714, 2021). "Additionally, A-485 led to dramatic and significant repression (ranging from 44% to 75% versus control) of HR in CREBBP or EP300 mutant HNSCC and lung-cancer cell lines, but not in wild-type cells." (PMID 34732714, 2021).
melanoma (52 papers, 2007 to 2025). A malignant, usually aggressive tumor composed of atypical, neoplastic melanocytes. "The deacetylation of EP300 was associated with a decrease in its HAT activity (as measured by acetylation of histone H4) in two independent melanoma cell lines." (PMID 38030596, 2023). "As expected, we found that the response rate was higher in EP300-mutated than that in EP300-wild-type cancers in three melanoma cohorts receiving ICI treatments." (PMID 34616736, 2021). "Remarkably, we found that the EP300 and SOX10 gene loci on chromosome 22 are frequently co-amplified in melanomas, including UV-associated and acral tumors." (PMID 38994683, 2024). "HDAC8 deacetylates EP300, a histone acetyltransferase, leading to its inactivation and increased melanoma cell invasion." (PMID 39200315, 2024). "The high frequency of EP300/SOX10 co-amplification identified in human melanomas and previous data from our group demonstrating that EP300 KD leads to decreased SOX10 protein levels strongly suggest a functional relationship between EP300 and SOX10." (PMID 38994683, 2024). "We first determined the expression levels of EP300 and CREBBP across a panel of melanoma cell lines that were either sensitive or resistant to BRAFi therapy and found that cell lines that were sensitive to inhibitor therapy had increased EP300 levels." (PMID 38030596, 2023). "Silencing of EP300 through shRNA knockdown increased the invasion of melanoma cells into 3D collagen matrices whereas overexpression of EP300 decreased cell invasion." (PMID 38030596, 2023). "As the HDAC8 expressing cells are highly invasive, we next examined if modulating EP300 expression would alter the invasive capacity of melanoma cells." (PMID 38030596, 2023). "Inhibition of EP300 increases melanoma cell invasion, resistance to stress and increases melanoma brain metastasis development." (PMID 38030596, 2023). "Functional studies were then undertaken to determine if inhibition of EP300 (mimicking its deacetylation by HDAC8) would alter sensitivity of melanoma cells to BRAFi therapy." (PMID 38030596, 2023). "The expression of the p300 gene, EP300, is often upregulated, as it is located in regions of chromosomal copy gain seen in melanomas." (PMID 35326683, 2022). "Recently, a study in China showed that, compared with other subtypes, EP300 copies in limb melanoma increased more frequently, and 30% (70/233) of AM lesion samples carried the copy number gains of the EP300-MITF axis." (PMID 36125617, 2022). "MITF is a downstream target of EP300, a histone acetyltransferase and an oncogene in a subset of melanomas." (PMID 33556121, 2021). "Kim and colleagues recently demonstrated that melanoma growth is driven by direct control of MITF by the evolutionary conserved master transcriptional coactivator EP300." (PMID 34067022, 2021). "For example, EP300 is actually upregulated in melanoma cell lines, and inhibition of KAT function in vitro reduces melanoma tumor cell growth." (PMID 24622842, 2014). "This shift facilitates increased EP300 interaction at JUN-transcriptional sites while reducing its association with melanocyte-inducing transcription factor sites, promoting melanoma cell invasion and resistance to stress, ultimately leading to enhanced metastatic potential." (PMID 40016470, 2025). "As we observed a strong association between MITFhigh expression and EP300/SOX10 co-amplification status, we sought to determine whether this trend was present in a larger set of melanoma cell lines using the CDM." (PMID 38994683, 2024). "In addition, 67.7% (32/51) of melanoma cell lines in the CDM dataset possessed more than two copies of both EP300 and SOX10, and we labeled these lines as EP300/SOX10 co-amplified." (PMID 38994683, 2024). "Previous studies have identified higher frequencies of gene amplifications in acral versus UV-associated melanomas; however, this does not seem to be the case for EP300." (PMID 38994683, 2024).
melanoma (continued). "Additionally, recent findings from Moffitt Cancer Center revealed that the HDAC8-mediated inhibition of EP300 drives a transcriptional state that significantly increases melanoma brain metastasis." (PMID 39200315, 2024). "We therefore suggest that EP300/SOX10 co-amplification in melanoma may serve as a biomarker for tumors which would benefit from therapeutic p300 inhibition." (PMID 38994683, 2024). "In addition to this, inhibition of EP300 also mimicked HDAC8 activation by promoting melanoma cell invasion and by increasing the formation of brain metastases in mice." (PMID 38030596, 2023). "Given the proximity of the EP300 and SOX10 loci and their significant roles in melanoma development and progression, we sought to explore a functional connection between these two genes in melanoma." (PMID 38994683, 2024). "Remarkably, we found that EP300 and SOX10 gene copy numbers are strongly correlated in human melanomas and are reproducibly co-amplified at a high frequency (∼35%–46% of samples) across several melanoma datasets from cBioPortal, including TCGA database." (PMID 38994683, 2024). "Because both EP300 and SOX10 have been shown to promote melanoma cell growth and co-bind on chromatin, it is possible that their co-amplification synergistically promotes melanoma cellular growth." (PMID 38994683, 2024). "Further studies demonstrated that silencing of EP300 through shRNA knockdown also protected WM164 and SK-MEL-28 melanoma cells from both UV irradiation and hypoxia." (PMID 38030596, 2023). "HDAC8 may modulate chromatin dynamics and gene expression in melanoma BrM by altering H3K27ac levels and enhancing accessibility at JUN binding sites through the deacetylation of EP300, effectively inactivating it." (PMID 40016470, 2025). "In MITFlow/DCTlow A375, Sk-Mel-24, and WM793 melanoma cells without EP300/SOX10 co-amplification, SOX10 protein expression was also found to be downregulated following treatment with A-485." (PMID 38994683, 2024). "Hao and his colleagues found that EP300 could induce an increase in ALKBH5 expression to reduce the m6A level of FOXM1 mRNA by upregulating H3K27ac, resulting in enhanced FOXM1 mRNA levels and EMT cascade activation in melanoma." (PMID 36276071, 2022). "Interestingly, data mining in the COSMIC database revealed that EP300-R1627W was found not only in TCC BCa in our study, but also in B-cell lymphoma, T-cell lymphoma-leukemia, colon adenocarcinoma, endometrial carcinoma, serous carcinoma, malignant melanoma, and gastric adenocarcinoma." (PMID 36647005, 2023). "In all cell lines tested, the presence of A-485 led to sharply lower SOX10 protein expression regardless of EP300/SOX10 amplification status, phenotype (MITFhigh vs. MITFlow), or melanoma subtype." (PMID 38994683, 2024). "Although the related gene set size did not allow to reach significance, the melanoma canonical pathway included two of them, namely PIK3CD and EP300." (PMID 34067022, 2021). "To investigate this, we classified melanoma cell lines as either EP300/SOX10 co-amplified (>2 copies of both EP300/SOX10) or not co-amplified, treated them with the potent and specific p300 KAT inhibitor A-485, and probed for SOX10 and downstream SOX10 target genes, such as MITF and DCT." (PMID 38994683, 2024).